INS (insulin)
Diseases named in the same sentence as INS in open-access papers (continued):
Sharing a sentence is not in itself a finding about the gene and the disease.
Insulin resistance (continued). "However, high IMCL levels do not necessarily lead to insulin resistance, since they are also present in skeletal muscle from endurance-trained athletes, who are highly insulin-sensitive." (PMID 25601841, 2014). "Because only a subgroup of obese Ossabaws exhibited deranged glucose homeostasis, future studies of insulin resistance should be performed in animals based on preoperative biochemical testing and validation of insulin resistance, not merely preoperative weight, as was done in this study." (PMID 25215301, 2014). "The amount of carbs in some of those assumed low carb might contain enough carbs to stimulate insulin secretion and induce insulin resistance while that of other low-carb diets is not sufficient to enhance insulin secretion and induce insulin resistance." (PMID 25055153, 2014). "Since insulin resistance would be expected to worsen with an increase in adiposity, this finding suggests some portion of the intervention may benefit insulin sensitivity independent of adiposity." (PMID 24433565, 2014). "To assess whether ghrelin, DAG and obestatin regulate thermogenesis and insulin resistance during aging, we measured circulating ghrelin, DAG, obestatin and insulin concentrations in young, middle-aged and old wild-type (WT) mice, under either fed or fasting conditions." (PMID 25543537, 2014). "Interestingly, there appeared to be a sizable number of cases of elevated fasting insulin levels (as an estimate of insulin resistance) in this sample that were not identified by ATP-III MetS or our MetS Z-score." (PMID 24755002, 2014). "Moreover, insulin resistance is not thought to influence beta cell function per se, it just leads to more insulin being produced." (PMID 24669786, 2014). "Hence, we hypothesize that the post-receptor crosstalk of GH and insulin signaling would have an effect on CUG and insulin resistance in SGA." (PMID 24963636, 2014). "Whilst there is inconsistency as to which component of the insulin-mediated glycolytic pathway is affected in GCs in women with PCOS, excessive serine phosphorylation has been attributed to the post-binding defect and insulin resistance observed in these women." (PMID 25139174, 2014). "That long-term or continuous insulin exposure could lead to insulin resistance is not a new concept." (PMID 25259572, 2014). "Fasting insulin levels and non-fasting/fasting C-peptide levels may shadow the state of stress that the pancreas has in presence of insulin resistance." (PMID 24911052, 2014). "This suggests that glucose is higher during acute SD primarily due to insulin resistance of unknown etiology, rather than to a defect in insulin secretion related to pancreatic ER stress." (PMID 24102714, 2014). "Fgf21 expression in skeletal muscle, but not serum FGF21 levels was increased in HIV patients with lipodystrophy and this was correlated to insulin resistance, indicating that FGF21 is a myokine that may be correlated with insulin resistance in an autocrine/paracrine manner." (PMID 25071723, 2014). "Consistent with the previous study, the present study revealed that higher 25(OH)D concentration and CRF levels were related to lower levels of fasting insulin and insulin resistance, independent of obesity status (VFA levels), in middle-aged and elderly Japanese men." (PMID 25551248, 2014). "In this context, good glycemic control might have been relatively achieved among the second tertile of patients whose insulin secretion might have been modestly preserved and who might not have had insulin resistance." (PMID 25349635, 2014). "Moreover, there is no other calculator for insulin resistance that uses ELISA measured values of insulin." (PMID 31667161, 2014). "Our results have shown that induction of insulin resistance by fats from a high-fat diet (HFD) is prevented when insulin secretion is disrupted with streptozotocin, suggesting that dietary fat itself does not cause insulin resistance without insulin." (PMID 24741073, 2014).
Insulin resistance (continued). "Insulin therapy to overpower insulin resistance without eliminating excess calories may worsen ectopic lipid overload." (PMID 26237486, 2014). "The exact mechanism remains unknown, but results of numerous studies suggest that blueberry extracts improve insulin resistance in a manner that does not involve induction of insulin secretion." (PMID 25421245, 2014). "Strikingly, after 20 weeks on diet, the stabilization of adipose tissue inflammation was mirrored by comparable levels of fasting insulin and HOMA-IR, which on the one hand might support the notion that adipose tissue inflammation contributes to insulin resistance." (PMID 24438079, 2014). "Studies in adults suggest that CIH is primarily due to insulin resistance in spite of a situation of supranormal β-cell function, because beta cell could not secrete as much insulin as that necessary to compensate insulin resistance." (PMID 24628829, 2014). "However, diabetic animals often have “selective insulin resistance,” where insulin fails to suppress gluconeogenesis but retains its ability to activate lipogenesis." (PMID 25566193, 2014). "Moreover, palmitate-induced hepatic insulin resistance is dependant on the generation of mitochondrial ROS, demonstrating that the negative effect of ROS on insulin signalling is a phenomenon shared by a variety of metabolic tissues." (PMID 24672550, 2014). "Adapting knowledge from those studies to the African setting will significantly improve the prevention and control of insulin resistance related status, without necessarily measuring insulin sensitivity, which at present appear to be unreliable using advocated fasting estimators." (PMID 25106496, 2014). "We asked how important fat was in the development of insulin resistance induced by the chronic exposure to a pathological level of insulin (hyperinsulinemia) by depriving cells of exogenous (no sera was added) and endogenous fatty acids (by inhibition of fatty acid synthesis)." (PMID 25055153, 2014). "In addition, the values for Homeostatic Model Assessment used to quantify insulin resistance (HOMA-IR), were also significantly lower in the athletes (0.61±0.16 vs 1.16±0.51), indicating that they were, in general, more insulin-sensitive than the control participants." (PMID 24643011, 2014). "In addition, it has been reported that TNF-α is overexpressed in the adipose and muscle tissues of obese and insulin-resistant non-diabetic subjects, and overexpression is positively correlated with insulin resistance." (PMID 25548896, 2014). "However, the activity of the placental insulin signaling pathway was not altered, consistent with the possibility that the placenta of obese dams develops insulin resistance." (PMID 24744907, 2014). "In addition, this positively correlated with insulin resistance without altering insulin levels or related genes expressed in the liver." (PMID 24963636, 2014). "In mice without adiponectin, hepatic insulin resistance was observed in parallel with a decrease in therapeutic response to agonists of PPARγ, indicating that adiponectin is an important factor enhancing PPARγ-mediated improvement in insulin sensitivity." (PMID 24410812, 2014). "Type 2 diabetes does not involve a lack of insulin secretion but rather is characterized by insulin resistance, a state in which insulin has a reduced ability to mediate glucose homeostasis in its major target tissues, such as skeletal muscle, adipose tissue, and liver." (PMID 24748202, 2014). "Although the affinity of IGF-1R for insulin is lower compared with IGF-1, high concentrations of insulin, which are often observed in patients and animal models with insulin resistance, may affect intracellular signaling pathways dependent on IGF-1R or hybrid receptors." (PMID 25352918, 2014).
Insulin resistance (continued). "While the effect of insulin sensitivity on lifespan is complex – some insulin-resistant mice, such as mice lacking IRS1, are long lived – many long-lived mouse models have increased insulin sensitivity, and diet-induced insulin resistance shortens mammalian lifespan." (PMID 25059582, 2014). "Our data are in agreement with a previous study revealing blunted HFD-induced adipose and liver inflammation and ameliorated obesity-induced adipose and liver insulin resistance but no improvement in skeletal muscle insulin sensitivity in mice with haematopoietic cell-specific deletion of TLR4." (PMID 24203314, 2014). "It is proposed that insulin resistance is the critical determinant of the pro- or anti-inflammatory effect of insulin, because only liver, muscle, and fat tissue, but not leukocytes, become insulin-resistant." (PMID 24524669, 2014). "However, myeloid/haematopoietic cell-specific TLR4 knockout mice as generated by adoptive BM transfer were not protected from HFD-induced skeletal muscle insulin resistance, whereas hepatic insulin sensitivity was significantly improved." (PMID 24203314, 2014). "We have shown in in vitro, animal, and human studies that CN, aqueous extracts of CN, and CN polyphenols not only improve insulin function but also act as antioxidant and anti-inflammatory compounds to counteract the negative effects of insulin resistance and obesity." (PMID 24349472, 2013). "Neuronal insulin resistance is associated with several neurological disorders and recent evidence has indicated that dorsal root ganglion (DRG) neurons in primary culture display altered insulin signaling, yet in vivo results are lacking." (PMID 24252636, 2013). "In conclusion, we suggest that the normal adaptive response of the β-cell to insulin resistance involves an upregulation of the incretin system manifested as both increased islet GLP1R protein levels and enhanced GPR119-activated GLP1 secretion, resulting in improved β-cell insulin secretion." (PMID 23781322, 2013). "This is a lack of response of muscle, liver and other tissues to insulin in terms of glucose uptake from the blood, and is compensated for by an increase in pancreatic insulin secretion, so people that have insulin resistance tend to have higher fasting and non-fasting insulin levels." (PMID 23281938, 2013). "Although PWBC are an easily obtainable cell model which has been satisfactorily used as a good surrogate for studying gene expression changes in conditions of human insulin resistance and related abnormalities, they do not represent a typical insulin target tissue." (PMID 23894607, 2013). "However, values of insulin, other measures of insulin resistance, and hs-CRP levels did not correlate with soleus muscle IMCL content." (PMID 23863826, 2013). "It has been suggested that alterations in specific DAG species may differentially contribute to insulin resistance, and so these disturbances in DAG distribution in the Id2−/− males could contribute to the increased glucose uptake by altering insulin signaling." (PMID 24023810, 2013). "While levels of CCL2 did not correlate with insulin sensitivity in this study, it is known that CCL2 does cause insulin resistance when mice are infused directly with this chemokine, and there is some evidence that this is also the case in adult humans although the evidence is not conclusive." (PMID 23557387, 2013). "Despite the evidence suggesting that elevated plasma LPS could play a role in the pathogenesis of insulin resistance, it is not known whether LPS impairs insulin action on glucose metabolism in human muscle." (PMID 23704966, 2013). "However, it remains unknown whether PTEN, the major negative regulator of the insulin/PI3K pathway, is involved in chronic GH therapy induced insulin resistance." (PMID 23840818, 2013).
Insulin resistance (continued). "As discussed, many studies have suggested that TRB3 can induce insulin-resistance; thus, it will be of interest in the future to evaluate whether constitutive TRB3 knockout alters insulin signaling and fasting glucoses in murine models of Type 1 and 2 diabetes." (PMID 24490110, 2013). "However, why the continued insulin elevation did not result in hypoglycemia suggests the development of a degree of insulin resistance." (PMID 23984046, 2013). "Insulin resistant morbid obese (IR-MO) subjects when compared to non insulin-resistant morbid obese (NIR-MO) group showed significantly larger waist circumference and higher levels of fasting insulin, HOMA-IR, HbA1C and CRP, while HDL cholesterol levels were lower." (PMID 24138787, 2013). "Therefore, we focused mainly on its relationship with insulin-resistant states in this study, although some reports have shown that RBP4 could play a more important role in lipid metabolism than in insulin resistance." (PMID 23671852, 2013). "In a subsequent study on 645 nondiabetic individuals from Italy, early insulin secretion adjusted for the level of insulin resistance (i.e., the disposition index (DI)) was shown to be significantly reduced in individuals carrying the R84 variant compared with homozygous QQ carriers." (PMID 23762820, 2013). "Furthermore, C5L2−/− mice have altered glucose/insulin metabolism, adiponectin and insulin signalling gene expression in WAT, which could contribute to development of insulin resistance." (PMID 23630572, 2013). "There are evidences that a 50% reduction in content of PPARγ receptor did not result in insulin resistance, as one might predict, but rather led to an increase in insulin sensitivity." (PMID 24330836, 2013). "However, it has been suggested that the expression of CES1 mRNA in human adipose tissue is correlated with measures of adiposity and metabolic function including waist circumference, homeostasis model assessment-insulin resistance (HOMA-IR), triglyceride level, and plasma insulin level." (PMID 23468884, 2013). "In contrast to our hypothesis, the lack of functional AMPK did not influence insulin-stimulated glucose uptake with ageing or exacerbate insulin resistance after high fat feeding in old mice." (PMID 23671593, 2013). "However, in the present study, the Matsuda index was not solely used to determine groupings since a clear cut-off point for classification of insulin resistance versus insulin sensitivity in Hispanic populations has not yet been defined." (PMID 24358323, 2013). "The primary mechanism in Patient A, who did not demonstrate features of insulin resistance, could have been an exaggerated and rapid increase of insulin release." (PMID 23424590, 2013). "Thus, it appears that the relationship between hepatic steatosis and insulin sensitivity differs by ethnicity, with hepatic steatosis not being integral to the pathogenesis of insulin resistance in black women." (PMID 23401754, 2013). "These alterations were sexually dimorphic with male EtOH-exposed offspring having some insulin resistance (as indicated by an elevated HOMA index under basal conditions and elevated first phase insulin secretion) and female EtOH-exposed offspring having increased insulin sensitivity." (PMID 23533642, 2013). "Two clinical trials indicated that oral magnesium supplementation could improve insulin sensitivity or insulin resistance in non-diabetic subjects." (PMID 24084051, 2013). "Similarly, there was a statistical positive association between fibrosis stage and higher levels of γ-GT (p = 0.003), insulin (p = 0.006) and HOMA-IR (p = 0.005), as well as progressively higher prevalence of insulin resistance (p = 0.009) and the metabolic syndrome (p = 0.029)." (PMID 22359625, 2012).
Insulin resistance (continued). "This may indicate reduced fat accumulation associated with increased insulin sensitivity in mice lacking NPP1, given the previously reported observations of insulin resistance and glucose intolerance in mice with over-expression of hepatic NPP1." (PMID 22359666, 2012). "As a result, insulin resistance produces a dysregulation of energy balance at the level of liver, adipose tissue, and muscle and, at the same time, favours the activated cells of the immune system since they do not become insulin resistant." (PMID 22701480, 2012). "The administration of insulin sensitizers, such as metformin and rosiglitazone, which were proposed in PCOS patients to improve ovulation induction and metabolic parameters, increased serum Hcy levels in patients with type 2 diabetes mellitus, despite the decrease in insulin resistance." (PMID 23843832, 2012). "However, it has been identified that hyperinsulinemia and insulin resistance were the major pathophysiologic conditions of type 2 diabetes but not lack of insulin as previously considered." (PMID 22848482, 2012). "In addition, other surrogate indicators of insulin resistance were not affected by Pioglitazone treatment on day-14, including fasting serum insulin; C-peptide; SHBG; resistin; and adiponectin." (PMID 22412837, 2012). "It is also possible that other factors not assessed here, including insulin and adipokine concentrations, insulin resistance, and other markers of glycaemic control may partly explain the associations observed." (PMID 22831708, 2012). "To date, although a number of drugs have been developed to control various targets related to the pathway of insulin secretion and insulin resistance, there is no commercially available medication that effectively modulates the glucagon-signaling pathway in humans." (PMID 23226550, 2012). "Furthermore, RBP4 level was increased in serum of lean and obese insulin-resistant humans compared to insulin-sensitive humans, indicating that higher RBP4 may reflect insulin-resistance independently of obesity." (PMID 23119072, 2012). "Similarly, the lack of data on insulin levels precluded a direct analysis of the relationship between hepcidin and estimates of insulin resistance." (PMID 23144745, 2012). "In leptin resistance, glucose-stimulated insulin secretion is not suppressed by leptin, which may lead to insulin resistance." (PMID 22533665, 2012). "In addition, insulin-stimulated glucose uptake, representing peripheral insulin resistance, was not significantly different among the groups of Px rats." (PMID 22550941, 2012). "Also, BPA levels were found to be associated with abnormal liver function enzymes and higher levels of fasting glucose, insulin, and HOMA-IR (homeostasis model of assessment—insulin resistance), all points suggesting that BPA may have a role in CVD." (PMID 22645278, 2012). "Legro etal., concluded fasting G: I (glucose/Insulin) ratio is maybe useful as a screening test for insulin resistance in obese non-Hispanic white PCOS women, with the highest sensitivity and specificity." (PMID 22405326, 2012). "We did not measure insulin levels and neither evaluated homeostasis model assessment of insulin resistance index (HOMA IR), which could be helpful in establishing the presence of metabolic syndrome, what could explain variations in VCAM-1 levels." (PMID 23113882, 2012). "Overweight and obesity are major contributors to the development of insulin resistance and impaired glucose tolerance; when β-cells are no longer able to secrete enough insulin to overcome insulin resistance, impaired glucose tolerance progresses to type 2 diabetes." (PMID 23316348, 2012). "Meanwhile, compared with control rats, the HFD increased body mass, epididymal fat mass, blood insulin concentration, blood total cholesterol and free fatty acid concentrations, but reduced Kitt, 3MG uptake and glycogen content, confirming the HFD used induced insulin resistance." (PMID 23272147, 2012).